ACHE (acetylcholinesterase (Yt blood group))
Diseases named in the same sentence as ACHE in open-access papers (continued):
Sharing a sentence is not in itself a finding about the gene and the disease.
Anxiety (continued). "In this context, a SNP in the 3′-untranslated region (3′-UTR) of ACHE (rs17228616) attenuates AChE mRNA’s interaction with the primate-specific miRNA-608, and homozygous carriers of this SNP display elevated anxiety and hypertension." (PMID 36117917, 2022). "In vivo studies that were obtained by exposure to TCS (0.3 and 0.6 mg/L) of adult zebrafish for 48 h showed that it induced anxiety-like behavior by reducing acetylcholinesterase (AChE) activity in the brain." (PMID 35740142, 2022). "Studies with physostigmine (an AChE inhibitor) also suggested that proper levels of cholinergic tone in the MS or HPC are essential for maintaining proper levels of innate anxiety in rats." (PMID 34305537, 2021). "It is feasible that overlapping genes mediate ventral hippocampus AChE activity and anxiety-like behavior." (PMID 34733190, 2021). "The previous study in mice has found that anxiety was linked to AChE activity by demonstrating that pubertal BPA (Bisphenol A) exposure increased anxiety-like behavior and decreases AChE activity in the hippocampus." (PMID 32093039, 2020). "TEO ameliorated Sco-induced increasing of AChE activity, amnesia, anxiety, and reduced the brain antioxidant capacity." (PMID 33158153, 2020). "Further, recent research suggests that anxiety-like behavior is also directly associated with the acetylcholinesterase (AChE) activity of the hippocampus since AChE knockdown in the hippocampus promotes anxiety-like behavior in mice." (PMID 32093039, 2020). "Increased ACh levels by inhibiting acetylcholinesterase (AChE) in the hippocampus of mice induce anxiety-like and depression-like behaviors." (PMID 33384583, 2020). "This study showed that REO counteracts cognitive performance decrease and anxiety increase resulting from Sco treatment through a mechanism implying mitigation of brain oxidative stress and regulation of AChE activity." (PMID 31936730, 2020). "In the second set of analyses, CsAE was also investigated for its eventual capacity to abolish anxiety, memory deficits, brain oxidative stress and to inhibit AChE in a 6-OHDA zebrafish model of PD." (PMID 32276477, 2020). "In this context, miR-132 is especially suitable, as its interaction with AChE had been shown to control anxiety." (PMID 28667373, 2018). "The level of AChE enzyme increases in anxiety and depression." (PMID 41502474, 2026). "Moreover, both formulations alleviated pain and anxiety behaviors while restoring AChE activity and decreasing oxidative stress in the cerebral cortex." (PMID 41011247, 2025). "Taken together, lower anxiety (greater light exposure in LDT) and enhanced spatial exploration (Y-maze novel arm entry) were associated with a stronger antioxidant profile (SOD ↑) and reduced oxidative/cholinergic stress (MDA ↓, AChE ↓)." (PMID 41155598, 2025). "Notably, 4-PSCO NC and 4-PSCO NE treatments reversed pain symptoms and anxiety-like behavior in the animals, restored AChE activity, and alleviated oxidative stress." (PMID 41011247, 2025). "Alterations in exertion of AChE might be associated with heightened oxidative stress induced by BHA, leading to the observed anxiety in this study." (PMID 40700163, 2025). "Anxiety-like behaviors are directly related to AChE activity in the hippocampus, and NP exposure may disrupt this activity." (PMID 39195719, 2024). "Anxiety- and depression-like behaviors are well correlated with AChE inhibition." (PMID 38098499, 2023). "The increased transfer latency and decreased entries to the open arm in the GAL group suggested anxiety-induced behavioral inhibition, as previous studies reported that increased acetylcholine levels following the inhibition of AChE in mouse hippocampus induced anxiety-like behaviors." (PMID 37371449, 2023). "In addition, exposure to acute NS elevates the AChE activity in a compensatory way in the hippocampus, which is attributed to anxiety, depression-like behaviors and memory deficits in stressed animals." (PMID 37512501, 2023).
Anxiety (continued). "Rodent experiments also confirmed that increasing ACh via the acute administration of physostigmine induced anxiety-like and depressive behaviors, and prolonged treatment with the 5-hydroxytryptamine (5-HT) antidepressant fluoxetine increased AChE activity, particularly in the hippocampus." (PMID 36430254, 2022). "We demonstrated that L. selago could improve memory and decrease anxiety by restoring brain oxidative stress and regulation of AChE activity." (PMID 34198639, 2021). "Furthermore, an increase in AChE activity correlated with a decrease in anxiety behaviors in mice in OFT." (PMID 34502198, 2021). "Rho could alleviate anxiety, memory deficits, and brain oxidative stress in Sco-treated zebrafish and could regulate the cholinergic function by inhibiting the AChE activity." (PMID 32635149, 2020). "Furthermore, pharmacological and molecular genetic decreases in hippocampal AChE activity increased anxiety-like behaviors." (PMID 33384583, 2020). "These might have contributed to the psycho-cognitive deficits and increased anxiety-like behaviors that were observed following AChE inhibitions in the studied brain regions." (PMID 30513797, 2018). "In normal animals, a recent study found that chronic administration of fluoxetine increased hippocampal AChE activity, while knockdown of AChE in the hippocampus increased anxiety-like behaviour in the elevated plus-maze, suggesting an anxiogenic effect of hippocampal AChE inhibition." (PMID 26769042, 2016). "Animals showed anxiety-like behavior and this behavior as well as the AChE chromatine structure and the entire HDAC enrichment profile were reversed by NaBu, an HDAC inhibitor; the restoration of mE1c expression level was however due to HDAC4 inhibition entirely." (PMID 26300730, 2015). "The researchers did not detect any associations between AChE inhibition and anxiety symptoms." (PMID 38098750, 2023). "This suggests that increased AChE activity may predict greater levels of anxiety." (PMID 34733190, 2021). "The current study, which specifically localized changes in AChE transcript expression to two major limbic structures involved in regulating the behavioral response to stress, supports the role of altered AChE transcript expression in the delayed exacerbation of anxiety and depression." (PMID 25972795, 2015). "Cotreated mice demonstrated improved memory, reduced anxiety and depressive‐like behavior, and enhanced antioxidant systems, as evidenced by normalized SOD, CAT, and GPx and lowered MDA and AChE activity." (PMID 41394883, 2025). "There was a significant decrease in Acetylcholinesterase (AChE) activity and serotonin levels with an increase in concentration of BHA, leading to a dose-responsive increase in anxiety and impairment in memory." (PMID 40700163, 2025). "OmEO can enhance memory through AChE inhibition, reduce SCOP-induced anxiety by increasing the time spent in the top zone in the NTT, and significantly reduce oxidative stress markers." (PMID 39858532, 2025). "The findings provided evidence that PGEO possesses the capability to enhance memory by AChE inhibition, alleviate SCOP-induced anxiety during behavioral tasks, and diminish brain oxidative stress." (PMID 38931080, 2024). "For example, electrolytic lesion of the MS, which decreased AChE activity in the HPC, reduced anxiety of rats during successive alleys tests (innate anxiety) and reduced freezing in contextual conditioned fear (learned fear)." (PMID 34305537, 2021). "Furthermore, the obtained data accomplished the proposed objectives, showing that CsAE attenuated memory deficits and anxiety resulting from 6-OHDA treatment by a mechanism implying restoring of brain antioxidant status and regulation of AChE activity." (PMID 32276477, 2020).
Anxiety (continued). "Moreover, E100 modulated disturbed anxiety levels, but failed to modulate hyperactivity parameters, whereas the reference AChE inhibitor donepezil (DOZ, one milligram per kilogram) significantly obliterated the increased hyperactivity measures of tested mice." (PMID 32872194, 2020). "On the other hand, despite the reduction of locomotor activity and AChE and NE in the brain of IPD and IPD + CPS-exposed rats, no significant changes were recorded in the SAP and grooming in the OPT or the anxiety index in EPM in these groups." (PMID 37235246, 2023). "In our study, no inhibitory effect of DEP on the activity of AChE was found, and the enriched Adlercreutzia in the DEP-L group was shown to be negatively correlated with anxiety behavior." (PMID 31137755, 2019).
myasthenia gravis (49 papers, 2011 to 2026). Myasthenia gravis (MG) is a rare, clinically heterogeneous, autoimmune disorder of the neuromuscular junction characterized by fatigable weakness of voluntary muscles. "AChE inhibitors were initially utilized in the treatment of myasthenia gravis, a neuromuscular condition associated with loss of ACh receptors at the neuromuscular junction, followed by skeletal muscle weakening." (PMID 37110594, 2023). "Loss of AChE complex proteins (or their activities) may lead to the dissolution of the complex and AChR receptor, as in myasthenia syndrome and myasthenia gravis." (PMID 41150528, 2025). "Many GAs exhibit acetylcholinesterase (AChE) inhibitory activity, which is associated with the treatment of several diseases such as Alzheimer’s disease (AD), Myasthenia gravis, and glaucoma as well as the mechanisms of insecticidal activity and anthelmintic drugs." (PMID 31010145, 2019). "For instance, treatment with pyridostigmine bromide, an AChE inhibitor used clinically for myasthenia gravis, improved outcomes in a murine Trypanosoma cruzi infection model, with effects attributed to cholinergic modulation of host immune responses." (PMID 41463687, 2025). "Pyridostigmine and neostigmine are the most used AChE inhibitors for the treatment of myasthenia gravis, but pyridostigmine is preferred because of its longer duration of action and lower potential for adverse gastrointestinal effects." (PMID 36937006, 2023). "AChE also represents a therapeutic target for controlling glaucoma, Parkinson’s disease, senile dementia, myasthenia gravis, and ataxia." (PMID 37110594, 2023). "For example, 12 patients were wrongly diagnosed with myasthenia gravis due to decremental EMGs, a positive response to injectable AChE inhibitors, or a partial response to oral AChE inhibitors." (PMID 37239850, 2023). "Cholinesterase (ChE), divided into two enzymes acetylcholinesterase (AChE) and butyrylcholinestarase (BChE), have been identified as potential targets in the treatment of AD, myasthenia gravis and glaucoma." (PMID 35701630, 2022). "Pyridostigmine is a reversible AChE inhibitor and a cholinergic drug in current clinical use for the treatment of myasthenia gravis." (PMID 34017249, 2021). "The short-acting AChE inhibitor (AChEI) edrophonium chloride (Enlon®, Tensilon®) is used for diagnosis of myasthenia gravis, because it leads to dramatic amelioration of the functioning of a particularly weak muscle group immediately after administration." (PMID 29534488, 2018). "Currently available drugs for inhibiting either AChE alone or in combination with BChE are available for the treatment of AD, myasthenia gravis and other conditions." (PMID 24893223, 2014). "The treatment approach of inhibiting peripheral AchE for myasthenia gravis had effectively proven that AchE inhibition was a reachable therapeutic target." (PMID 22216416, 2012). "Inhibition of AChE was considered to be achievable as a therapeutic target because of proven efficacy of inhibition of peripheral AChE as a treatment for myasthenia gravis (MG) proving that the approach was feasible." (PMID 22216416, 2012). "This study suggests that flavonoids, as AChE inhibitors, have the potential to improve neuromuscular transmission and may be of significant importance for the treatment of myasthenia gravis." (PMID 41267743, 2025). "AChE inhibitors enhance neuromuscular transmission by increasing the concentration of ACh in the neuromuscular junction, thereby improving the symptoms of myasthenia gravis." (PMID 41267743, 2025). "Acetylcholinesterase (AChE) is the key enzyme in the breakdown of acetylcholine, and its inhibition is a target for the treatment of Alzheimer’s disease and other neurological disorders including senile dementia, myasthenia gravis, and ataxia." (PMID 36771650, 2023).
myasthenia gravis (continued). "Changes in the homeostasis of ACh and its destruction by AChE involve numerous impairments such as muscular dystrophy, motor neuron diseases such as amyotrophic lateral sclerosis, congenital myasthenias and myasthenia gravis." (PMID 35455397, 2022). "Thus, novel AChE inhibitors with more favorable efficacy/safety profiles are being developed for the symptomatic treatment of myasthenia gravis." (PMID 29534488, 2018). "Thus, as in other diseases (e.g. myasthenia gravis), AChE over-expression is accompanied by changes in alternative splicing from the common AChE-S to the normally rare AChE-R variant." (PMID 22174879, 2011). "Neostigmine, a widely used inhibitor against AChE that can suppress the activity of AChE and prolong the action time of ACh effectively, is clinically applied to antagonize muscle relaxation effect after surgery and treat patients with myasthenia gravis (MG)." (PMID 34658849, 2021). "The response, however, is not immediate, unlike myasthenia gravis or CMS that respond to AChE inhibitors." (PMID 37176748, 2023).
amnesia (44 papers, 2014 to 2025). Pathologic partial or complete loss of the ability to recall past experiences ( AMNESIA, RETROGRADE) or to form new memories ( AMNESIA, ANTEROGRADE). "The increased AChE activity caused the degradation of acetylcholine and produced cholinergic deficiency, which results in amnesia." (PMID 35458662, 2022). "Scopolamine-induced amnesia was associated with increased oxidative stress and acetylcholinesterase (AChE) activity in mouse brains." (PMID 36005148, 2022). "In the context of SPA-induced amnesia, higher AChE activity is observed, which negatively impacts memory." (PMID 40429757, 2025). "Bisuracil 3c effectively inhibited brain AChE activity, reversing scopolamine-induced amnesia in mice at a dose of 5 mg/kg, which indicates its potential for cognitive enhancement." (PMID 40332440, 2025). "In the present study, we observed the effects of RDEO on learning and memory functions in the rat model of scopolamine‐induced amnesia, as well as the changes in AChE activity, M1 mAChR expression, and BDNF levels." (PMID 38688895, 2024). "Therefore, a modulator stimulating the action of AChE on ACh should ideally impair learning and memory through decreasing ACh levels in brain regions underlying cognitive function (such as the hippocampus and the neocortex), as scopolamine did in our amnesia groups." (PMID 38688895, 2024). "Rivastigmine, a common anti-amnesia medication being an AChE (acetyl cholinesterase) inhibitor, produced similar effects in the rats that received it as well." (PMID 37299107, 2023). "Higher concentration of β-amyrin is present in the B. ceiba leaf extract, which was reported to ameliorate various biochemical parameters (CAT, MDA, AChE) and cognitive functions in rats with scopolamine-induced amnesia." (PMID 36432418, 2022). "In another study, psoralen and iso-psoralen-rich extracts (0.1 and 0.3 mg/kg) of Psoraleae fructus improved amnesia in scopolamine-induced rats, apparently by AchE inhibition (IC50, 1.12 mM) and activation of cholinergic neuronal functions." (PMID 36432418, 2022). "The results from DPPH and reducing power assay suggested that besides inhibiting AChE, the combination also acts as a potent antioxidant which further aids as a complementary mechanism to counter amnesia." (PMID 34276370, 2021). "Because AChE inhibitors have potential in animal models of amnesia, attenuation of the brain AChE activity suggests that the HE confers anti-amnesic effects in mice treated with SCOP." (PMID 34204787, 2021). "Naringenin, purified from Citrus junos, is an AChE inhibitor and can ameliorate scopolamine-induced amnesia in mice." (PMID 35723391, 2021). "Because AChE inhibitors have potential in animal models of amnesia, attenuation of AChE activity in the brain suggests that the LS confers anti-amnesic effects in fish treated with SCOP." (PMID 34198639, 2021). "Gallic acid is also able to reverse the scopolamine-induced amnesia in mice, probably through inhibiting oxidative stress and decreasing acetylcholinesterase (AChE) enzyme activity in the brain." (PMID 31156781, 2019). "Piracetam significantly lowered (p < 0.001) the brain AChE activity as compared with the scopolamine-induced amnesia group." (PMID 31781268, 2019). "Overall, these findings suggest that ODH has anti-amnestic potential via activation of BDNF and p-CREB and inhibition of AChE in mice with scopolamine induced amnesia." (PMID 29370115, 2018). "Since BuPC antagonized the scopolamine-induced amnesia, its effect on AChE enzyme activity in brain homogenate was examined by using Ellman’s method." (PMID 29875670, 2018). "To investigate the possible mechanisms of YJT against the scopolamine injection-induced amnesia, we measured the hippocampal protein levels of AChE activity and BDNF." (PMID 29507588, 2018). "It has been previously reported that the herbal extract or any compounds reverse the amnesia induced by scopolamine have the potency to inhibit the activity of AChE enzyme." (PMID 29875670, 2018).